NARS2 (asparaginyl-tRNA synthetase 2, mitochondrial)
Description:
Mitochondrial aminoacyl-tRNA synthetase that catalyzes the specific attachment of the asparagine amino acid (aa) to the homologous transfer RNA (tRNA), further participating in protein synthesis. The reaction occurs in a two steps: asparagine is first activated by ATP to form Asn-AMP and then transferred to the acceptor end of tRNA(Asn) (Probable).
Synonyms: AsnRS; FLJ23441; SLM5; DFNB94
Tractability: PROTAC: ubiquitination databases record sites on it; its protein half-life has been measured.
Gene: Protein-coding gene on chromosome 11 (78,435,620 to 78,575,194, reverse strand). Ensembl gene ENSG00000137513.
Subcellular location: Mitochondrion matrix; Mitochondrion
Subcellular location (Human Protein Atlas): Mitochondria; Cytosol; Nucleoplasm
Pathways (Reactome):
Metabolism of proteins: Mitochondrial tRNA aminoacylation
Gene Ontology:
Molecular function: asparagine-tRNA ligase activity; aminoacyl-tRNA ligase activity; ATP binding; nucleic acid binding; nucleotide binding
Biological process: asparaginyl-tRNA aminoacylation; tRNA aminoacylation for protein translation
Cellular component: mitochondrion; mitochondrial matrix
Genetic constraint (gnomAD): Loss-of-function variants: 25 observed, 27.85 expected, observed/expected ratio (o/e) 0.9, 90% interval 0.65 to 1.25. The upper end of that interval is the gene's LOEUF score, 1.25, which puts it in group 5 of 6, group 1 being the genes least tolerant of losing a copy. Missense variants: 348 observed, 354.86 expected, observed/expected ratio (o/e) 0.98, 90% interval 0.9 to 1.07. Synonymous variants: 124 observed, 129.4 expected, observed/expected ratio (o/e) 0.96, 90% interval 0.83 to 1.11.
Gene-disease validity (ClinGen):
ClinGen rates the evidence that NARS2 causes each of these diseases.
mitochondrial disease (autosomal recessive): Definitive.
Leigh syndrome (autosomal recessive): Limited. A progressive neurological disease defined by specific neuropathological features associating brainstem and basal ganglia lesions.
nonsyndromic genetic hearing loss (autosomal recessive): Limited.
Homologues: Orthologues: chimpanzee NARS2 (99% identical), macaque NARS2 (96% identical), dog NARS2 (88% identical), pig NARS2 (87% identical), guinea pig NARS2 (87% identical), rabbit NARS2 (86% identical), rat Nars2 (85% identical), mouse Nars2 (84% identical), zebrafish nars2 (66% identical), tropical clawed frog nars2 (62% identical), Drosophila melanogaster AsnRS-m (38% identical), Caenorhabditis elegans nars-2 (33% identical). Paralogues in human: NARS1 (29% identical), DARS1 (25% identical), DARS2 (22% identical), KARS1 (19% identical).
Diseases named in the same sentence as NARS2 in open-access papers:
NARS2 is named in the same sentence as 63 diseases in open-access papers, as found by Europe PMC text mining. Sharing a sentence is not in itself a finding about the gene and the disease. The quoted sentences say what the papers report.
epilepsy (11 papers, 2015 to 2025). A brain disorder characterized by episodes of abnormally increased neuronal discharge resulting in transient episodes of sensory or motor neurological dysfunction, or psychic dysfunction. "Our findings expand the mutational spectrum of NARS2 and highlight the associated phenotypic heterogeneity, underscoring the critical role of NARS2 in epilepsy and neurodevelopmental processes." (PMID 40264468, 2025). "NARS2 encodes a mitochondrial aminoacyl-tRNA synthetase crucial for protein synthesis, and its mutations disrupt energy metabolism, leading to epilepsy." (PMID 40264468, 2025). "The GAB2 insertion is near the adjacent gene NARS2, which has often been associated with epilepsies in human infants and children." (PMID 39596674, 2024). "Recent findings have identified two novel missense variants in the NARS2 gene in a patient with early-onset epilepsy and cardiac abnormalities." (PMID 39061374, 2024). "Biallelic variants in NARS2 were reported with disorders such as Leigh syndrome, deafness, epilepsy, and severe myopathy." (PMID 38310242, 2024). "A previous study reported a patient with novel NARS2 variants, causing infantile-onset severe epilepsy." (PMID 36918699, 2023). "Biallelic NARS2 mutations can cause various neurodegenerative diseases, leading to growth retardation, intractable epilepsy, and hearing loss in early infancy and further progressing to spastic paraplegia, neurodegeneration, and even death." (PMID 36620461, 2022). "Additional NARS2-linked phenotype includes intellectual disability, epilepsy, and severe myopathy, all exhibited by the proband." (PMID 35004675, 2021). "Since then, mutations of 14 other mt-aaRSs have been associated with mitochondrial disease, including NARS2, which has recently been linked to intellectual disability, epilepsy and myopathy." (PMID 25807530, 2015). "Future studies will explore the mechanistic differences in tissue-specific phenotypic expression of NARS2 mutations causing Leigh syndrome, hearing loss, epilepsy and intellectual disability." (PMID 25807530, 2015). "Additionally, mitochondrial drug cocktail therapy may be beneficial for epilepsy caused by NARS2 mutations." (PMID 40264468, 2025). "Our study expands the genotype spectrum of COXPD24 and highlights the critical role of NARS2 in epilepsy and neurodevelopment." (PMID 38310242, 2024). "Biallelic pathogenic variants in NARS2 cause COXPD24, a clinically heterogeneous disorder characterized by early-onset epilepsy, global developmental delay, abnormal muscle tone, progressive encephalopathy, sensorineural hearing loss, cardiomyopathy, and elevated lactate levels." (PMID 41426993, 2025). "Progressive mitochondrial encephalopathy manifesting as developmental delay, regression, epilepsy, myoclonus, dystonia, and spasticity due to a novel compound heterozygous variant in NARS2 has not been reported." (PMID 37746452, 2023).
hearing loss (7 papers, 2015 to 2024). "DFNB94 is characterized by bilateral nonsyndromic sensorineural hearing loss because the NARS2 protein is expressed in the spiral ganglion and other cells of the organ of Corti." (PMID 39442262, 2024). "Biallelic mutations in NARS2 have been recently identified in patients with hearing impairment, intellectual disability, seizures, hypotonia, delayed neurodevelopment, renal dysfunction, and/or liver involvement." (PMID 39335669, 2024). "The phenotypic variability of NARS2-associated disorder is broad, ranging from neurodevelopmental disorders to hearing loss." (PMID 37950505, 2023). "Patients with biallelic NARS2 mutations usually had bilateral sensorineural hearing impairments (75%, 15/20) in early life (first 3 months), followed by different types of seizures (95.6%, 22/23) within 1 year of age, mainly status epilepticus." (PMID 36620461, 2022). "Our findings establish lesions in NARS2 as a new cause for nonsyndromic hearing loss and Leigh syndrome." (PMID 25807530, 2015). "Here we report three mutations in NARS2, a mitochondrial asparaginyl-tRNA synthetase, associated with non-syndromic hearing loss (NSHL) and Leigh syndrome in two independent families." (PMID 25807530, 2015). "Dysfunction of some mitochondrial aminoacyl-tRNA synthetases (encoded by the KARS1, HARS2, LARS2 and NARS2 genes) results in a great variety of phenotypes ranging from non-syndromic hearing impairment (NSHI) to very complex syndromes, with a predominance of neurological signs." (PMID 39062730, 2024).
Leigh syndrome (7 papers, 2015 to 2025). "Mutations in the NARS2 gene are autosomal recessive and cause nonsyndromic auditory neuropathy as well as Leigh syndrome, an early-onset progressive neurodegenerative disorder affecting the CNS." (PMID 36529647, 2022). "In conclusion, our findings implicate mutant alleles of NARS2 as another cause of Leigh syndrome as well as DFNB94 hearing loss in humans." (PMID 25807530, 2015). "Our report therefore adds NARS2 to the list of mt-aaRS associated fatal epileptic mitochondrial encephalopathy and represents the second Leigh syndrome associated mt-aaRS." (PMID 25807530, 2015). "Our WES analysis reveals three heterozygous nuclear variants, MTFMT, NARS2, and EARS2, mapping in genes known to cause COXPD associated with Leigh syndrome." (PMID 35004675, 2021). "Together with the OCR measurements, the results from these functional studies revealed that Leigh syndrome and DFNB94 associated alleles impair the mitochondrial function of NARS2." (PMID 25807530, 2015). "Our mitochondrial metabolic and morphometric analyses lend credence to the three heterozygous variants, MTFMT, NARS2, and EARS2, mapping in genes linked to COXPD associated with Leigh syndrome, as a probable cause of the proband’s neurological manifestations and mitochondrial etiology." (PMID 35004675, 2021). "Furthermore, along with mutations that affect NARS2 enzymatic function, decreased levels of NARS2 mRNA and protein are observed in fibroblasts from individuals with Leigh syndrome." (PMID 29125828, 2017). "Mutations in the NARS2 gene, downregulated in the FRDA cohort, are known to cause a spectrum of clinical phenotypes, including non-syndromic hearing loss, myopathy, and the mitochondrial energy deficiency disorders Leigh syndrome and Alpers syndrome." (PMID 29125828, 2017). "A hypothetical truncated NARS2 protein, secondary to the Leigh syndrome mutation p.Tyr323* is not detectable and p.Asn381Ser further decreases NARS2 protein levels in patient fibroblasts." (PMID 25807530, 2015). "The nonsense Leigh syndrome mutation did not result in a truncated NARS2 protein product in patient fibroblast, which is indicative of nonsense mediated NARS2 mRNA decay." (PMID 25807530, 2015).
autosomal recessive deafness 94 (5 papers, 2022 to 2024). "NARS2 mutations are associated with a combined oxidative phosphorylation deficiency 24 and autosomal recessive deafness-94." (PMID 38919950, 2024). "Mutations in NARS2 are associated with combined oxidative phosphorylation deficiency 24 and autosomal recessive deafness." (PMID 36918699, 2023). "NARS2 gene variations were identified in patients with autosomal recessive deafness and COXPD24, and most of them were missense." (PMID 38310242, 2024). "Homozygous mutations in NARS2 have been associated with Combined Oxidative Phosphorylation Deficiency 24 (COXPD24) and autosomal recessive Deafness 94 (DFNB94)." (PMID 39442262, 2024). "However, nonsyndromic autosomal recessive deafness 94 (DFNB94), with which only one family is known to be affected, has also been reported concerning NARS2." (PMID 36523694, 2022).
deafness (4 papers, 2022 to 2025). An inherited or acquired condition characterized by the complete loss of the ability to hear from one or both ears. "Our report demonstrates the association of a new pathogenic variant in mitochondrial asparaginyl-tRNA synthetase (NARS2) with nonsyndromic sensorineural hearing loss, thus confirming biallelic mutations in NARS2 as a cause of nonsyndromic deafness." (PMID 36523694, 2022). "Biallelic NARS2 variants have been reported to cause a wide spectrum of clinical presentations, ranging in severity from early‐onset COXPD‐24 to non‐syndromic deafness." (PMID 40887432, 2025). "Interestingly, of 118 deafness genes, several genes have been reported to be associated with auditory neuropathy, a hearing dysfunction characterized by impaired transmission of signal to the auditory nerve by the presynaptic inner hair cells, such as PJVK, NARS2, SLC17A8, DIAPH3 and DIAPH1." (PMID 37062025, 2023).
Alpers syndrome (3 papers, 2015 to 2021). A cerebral degeneration that results in progressive degeneration of grey matter in the cerebrum and has_symptom convulsions. "Variants in PARS2, CARS2, GABRB2, FARS2, and NARS2 were also reported in Alpers’ syndrome patients." (PMID 34690748, 2021). "With whole exome sequencing we have identified mutations in NARS2 and PARS2, the genes encoding the mitochondrial asparaginyl-and prolyl-tRNA synthetases, in two patients with Alpers syndrome." (PMID 25629079, 2015). "In recent years, with the advancement of genetic testing technology, Alpers syndrome caused by NON-POLG genes has also been continuously reported, including mitochondrial aminoacyl transfer RNA synthetase related genes (PARS2, CARS2, FARS2 and NARS2) and γ-GABA receptor related genes Gene (GABRB2)." (PMID 34690748, 2021).
cardiomyopathy (3 papers, 2015 to 2025). A disease of the heart muscle or myocardium proper. "The reported patient with cardiac dysfunction has same phenotype with our patient and persistent elevation of serum hepatic and myocardial enzymes, but further investigation is necessary to verify whether NARS2 variants lead to cardiomyopathy." (PMID 38310242, 2024). "Consequently, more patients need to be identified to determine whether gray matter degeneration with either tubulopathy or cardiomyopathy are hallmarks of defects in NARS2 and PARS2, respectively, or just examples of a wider clinical spectrum." (PMID 25629079, 2015).
developmental delay (3 papers, 2018 to 2025). "In summary, this case demonstrates that compound heterozygous variants in NARS2 can phenotypically manifest exclusively in the brain with intractable epilepsy, myoclonus, developmental delay, regression, hypotonia, cerebral atrophy, and hypomyelination, followed by tetraspasticity and dystonia." (PMID 37746452, 2023). "These diseases display a broad clinical spectrum and may be further complicated with other symptoms such as developmental delay (NARS2, PARS2), pontocerebellar hypoplasia (RARS2), visual impairment (FARS2) psychomotor delay (TARS2) and microcephaly (VARS2)." (PMID 29288497, 2018).
melanoma (3 papers, 2022 to 2026). A malignant, usually aggressive tumor composed of atypical, neoplastic melanocytes. "Recently, research has shown that NARS2 has an important impact on immune resistance and drug resistance in melanoma." (PMID 39335669, 2024). "By using the same pooled melanoma and NSCLC cohorts, we also discovered other mutations of the genes FAT1, COL3A1, NRAS, NARS2, DCC, and PTPRT were associated with better ICI response and outcome." (PMID 35884556, 2022). "CRISPR screening further showed that NARS2 and NDUFC2 are necessary for the proliferation of melanoma cells, highlighting these genes as potential therapeutic targets." (PMID 41636115, 2026).
Ataxia (2 papers, 2024). Ataxia refers to impaired coordination of voluntary muscle movement. "On the other hand, the loss of function of DARS, RARS, KARS, HARS1, SARS, and NARS2/PARS2 were reported to cause neurological diseases that share ataxic feature, indicating an important role of ARS function in the pathogenesis of ataxia." (PMID 38869703, 2024). "NARS2 and PARS2 pathogenic variants caused Alpers–Huttenlocher syndrome with ataxia." (PMID 38869703, 2024).
auditory neuropathy (2 papers, 2020 to 2023). A hearing disorder characterized by impaired transmission of signals through the auditory nerve, resulting in mild to severe hearing loss and poor speech perception. "Variants of NARS2 due to homozygous missense mutation cause mitochondrial respiratory chain deficiency, leading to auditory neuropathy due to a cellular damage notably of the SGNs (DFNB94)." (PMID 32290039, 2020). "The mitochondrial asparaginyl-tRNA synthetase (NARS2) mutation has also been associated with auditory neuropathy and Leigh syndrome, an early-onset progressive neurodegenerative disorders characterized by symmetric, bilateral lesions in the basal ganglia, thalamus and brainstem." (PMID 32290039, 2020).
diabetes (2 papers, 2024 to 2025). "This is the largest cohort of individuals with diabetes caused by NARS2 variants to be added to the literature, highlighting early‐onset diabetes as an important feature of COXPD‐24." (PMID 40887432, 2025). "The 8 individuals with homozygous disease‐causing NARS2 variants identified in this study had neurological features and other extra‐pancreatic features in addition to diabetes." (PMID 40887432, 2025). "The aim of this study was to identify recessive NARS2 disease‐causing variants in individuals with genetically unsolved diabetes diagnosed in the first 2 years of life." (PMID 40887432, 2025). "We identified homozygous NARS2 missense variants in 8/397 (2%) individuals with diabetes diagnosed <24 months of age." (PMID 40887432, 2025). "The specific cardiac dysfunction and neonatal diabetes phenotypes are supplied in NARS2 variant individuals." (PMID 38310242, 2024). "Diabetes has therefore now been identified in a total of 11 cases from 45 reported in the literature, thereby affecting 24% of known cases with disease‐causing NARS2 variants." (PMID 40887432, 2025). "Clinical characteristics of 11 individuals with diabetes and biallelic variants in NARS2." (PMID 40887432, 2025). "We used genome and targeted next‐generation sequencing to screen for rare, coding biallelic NARS2 variants in a cohort of 397 individuals diagnosed with diabetes <24 months of age of unknown genetic cause." (PMID 40887432, 2025). "Recessive loss‐of‐function NARS2 variants causing the multi‐system disorder Combined oxidative phosphorylation deficiency 24 (COXPD24) have recently been reported in 3 individuals with diabetes diagnosed between 3 days and 14 months of age." (PMID 40887432, 2025). "Recently, pathogenic variants in the nuclear gene, NARS2, which encodes an aminoacyl‐tRNA synthetase critical for protein synthesis in the mitochondria, have been identified in 3 individuals (including 2 siblings) with diabetes diagnosed between 3 days and 14 months of age." (PMID 40887432, 2025). "Further studies will be needed to understand how disruption of mitochondrial protein translation by the m.3243A>G variant and variants in NARS2, SARS2, and TARS2 affects the β‐cell, leading to monogenic diabetes." (PMID 40887432, 2025). "The identification of diabetes as a common feature in individuals with COXPD‐24 suggests an important role for NARS2 in pancreatic β‐cells." (PMID 40887432, 2025). "The identification of 8 probands with NDM caused by biallelic NARS2 variants in our study brings the total number of individuals with COXPD‐24 and diabetes to 11 (24%), establishing neonatal and early‐onset diabetes as a clinical feature of this disorder." (PMID 40887432, 2025).
Mitochondrial encephalopathy (2 papers, 2023 to 2025). "This case broadens the phenotypic and mutational spectrum of NARS2-associated COXPD24 and highlights the importance of evaluating large exon deletions and novel variants in infants with early-onset mitochondrial encephalopathy and epileptic manifestations." (PMID 41426993, 2025).
Alzheimer disease (1 paper, 2021). A progressive, neurodegenerative disease characterized by loss of function and death of nerve cells in several areas of the brain leading to loss of cognitive function such as memory and language. "NARS2, mutated in 1.9% of the total patients, was found to be involved in the prognosis of neurodegenerative disorders (e.g., Alzheimer’s disease)." (PMID 35087523, 2021).
breast carcinoma (1 paper, 2025). "To elucidate the intricate roles of ADK fusion genes in HR+/HER2‒ breast cancer, we identified several distinct fusion events involving ADK with 6 different partner genes: PCDH15, SEC24C, KAT6B, RSU1, NARS2, and LRMDA." (PMID 41213951, 2025).
Cachexia (1 paper, 2022). Severe weight loss, wasting of muscle, loss of appetite, and general debility related to a chronic disease. "Of the six proteins that showed significant differences between the patients with and without cachexia, three were lower (CNPD1, APOA4, DACH1) while three were higher (BCL3 NARS2, ATP13A4) in cachexia." (PMID 36080280, 2022).